RN7SL666P (RNA, 7SL, cytoplasmic 666, pseudogene)
Gene: Miscellaneous RNA gene on chromosome 20 (43,222,206 to 43,222,509, forward strand). Ensembl gene ENSG00000240639.
Homologues: Orthologues: chimpanzee Metazoa_SRP (92% identical), macaque Metazoa_SRP (81% identical). Paralogues in human: RN7SL2 (82% identical), RN7SL1 (81% identical), RN7SL3 (80% identical), RN7SL300P (79% identical), RN7SL147P (78% identical), RN7SL732P (78% identical), RN7SL444P (78% identical), RN7SL664P (78% identical), RN7SL177P (77% identical), RN7SL186P (77% identical), RN7SL493P (77% identical), RN7SL709P (77% identical), and 706 more.